IRF1 (interferon regulatory factor 1)
Diseases named in the same sentence as IRF1 in open-access papers (continued):
Sharing a sentence is not in itself a finding about the gene and the disease.
cancer (continued). "Hitherto, don’t have been reported that the DNMT3B binding in promoters results in an increased gene expression if not quite the opposite, hence, we focus on four downregulated genes with cis elements and functionally related to cancer, PPL1, IRF1, BRAF, and VAV3." (PMID 36460706, 2022). "The notably high overlapping ratios were discerned for TFs playing critical roles in transcription pre-initiation or RNA polymerase activities, e.g., UBTF, TAF1, and POLR2A, in addition to others, like E2F6, IRF1, and MYC, which are involved in cancer-related processes." (PMID 36092921, 2022). "Moreover, IRF-1 binds to TNF-related apoptosis-inducing ligand (TRAIL) promoter, enhancing TRAIL-mediated killing of cancer cells." (PMID 36226063, 2022). "In this study, we first demonstrated the relationship among PSMB8, PSMB9, PSMB10, PSME1, PSME2, and IRF1 in the immune micro-environment and immune score through TCGA whole cancer cohorts, and further, we proved the correlation between PSMB8, PSMB9, PSMB10, PSME1, PSME2, IRF1, and immune cells." (PMID 36700205, 2022). "Kanneganti’s group identified interferon regulatory factor 1 (IRF1) in both the myeloid and epithelial compartments could act as a master regulator of PANoptosis in the colon to induce cancer cell death, thus protecting against tumorigenesis in CAC." (PMID 36505474, 2022). "Meanwhile, the expression pattern of CD8, IRF-1, γH2AX, and PD-L1 between UC mucosa with and without dysplasia/colitic cancer was comparable." (PMID 34158547, 2021). "Furthermore, the key genes correlated with KMO, such as the MYD88, IRF1, IL-18, and CASP1 genes, manipulate the inflammation where many cancers arise." (PMID 34683090, 2021). "Of note, the antagonism of IRF1 function by mitogenic pathways is not restricted to cancer settings." (PMID 33668131, 2021). "Unlike PD-L1 negative regulators (HDAC1, HDAC2, and HDAC3), the expression ranks of PD-L1 and its positive regulators (EP300, CREBBP, IRF-1, and BRD4) negatively correlated to Grade Group in another study, suggesting an increase of function during cancer progression." (PMID 34830196, 2021). "Our in silico analysis using TCGA cohort revealed correlations between IRF1 and STAT1 or STAT2 mRNA in HNSCC and LUAD, suggesting that STAT1 and/or STAT2 may be mainly involved in PD-L1 expression in these cancers." (PMID 34069326, 2021). "Six overexpressed oncogenes including BCL2, NOTCH1, SOX4, and CTNNB1 and 10 downregulated tumor suppressor genes including PRKCB, IRF1, CYLD, and TGFB1 were identified as the targets of the DE miRNAs, which may promote cancer development." (PMID 34336826, 2021). "We hypothesize that the distinct actions of BCA2 over IRF1 may explain, at least in part, the different proposed roles for BCA2 in these cancers." (PMID 34589482, 2021). "In HRAS transformed murine fibroblasts, and RAS-transformed human cancer cells, MEK-ERK signaling was shown to negatively regulate IRF-1-dependent transcription of IRF1 and STAT2, thus hampering IFN responses, and supporting the replication of oncolytic vesicular stomatitis virus (VSV)." (PMID 33668131, 2021). "Hence, elucidating the mechanisms of regulation of IRF1 by BCA2 in different cellular contexts will bring us closer to understanding the relationship between BCA2, cancer development and prognosis." (PMID 34589482, 2021). "Among CD68+CD163+ TAMs also expressing the recently identified TREM2 marker, we could identify a CXCL10+IRF1+STAT1+ M1-type Mφ population (Cluster 9) shared between all cancer types." (PMID 34220848, 2021). "In addition, interactions between HIF-1 and IRF-1, and HIF-1 and STAT1 have also been reported in mice, and these regulate the expression of iNOS and induce apoptosis in cancer cells." (PMID 31937813, 2020). "Therefore, identifying the regulatory mechanism of IRF1 by Ras/MEK will have important implications not only in the field of oncolytic viruses but also in the field of virology, cancer biology and immunology." (PMID 27508303, 2016).
cancer (continued). "To test whether IRF1 is required for BV6-induced cell death, we monitored different parameters of cell death in a panel of IRF1-depleted cancer cell lines." (PMID 25501823, 2014). "TFPD1, E2F6, IRF1, and HMGA1 are upregulated in all cancer samples." (PMID 24564251, 2013). "IRF-1 has been demonstrated to directly mediate IFN-γ-induced apoptosis via activation of caspase-1 gene expression in IFN-γ-sensitive ovarian cancer cells and other cancer cells." (PMID 23420765, 2013). "Since IRF-1 is a central modulator of the expression of the CXCR3 ligand chemokines, this study reinforces the relevance of the IFN-γ/STAT-1/IRF-1 axis as a favorable prognostic factor in cancer." (PMID 21875439, 2011). "In addition to nucleophosmin (NPM1), which can inhibit IRF1 function, the interaction between IRF1 repressors, YB-1 (Y-box protein) and TRIM28 (tripartite motif-containing 28), which are both overexpressed in various cancer types, has also been reported." (PMID 22295238, 2011). "The activation or overexpression of STAT1 could upregulate iNOS signaling pathways by promoting interferon regulatory factor 1 (IRF1) expression, resulting in the induction of inducible nitric oxide synthase (iNOS or NOS2), which, in turn, improved the effect of cisplatin on cancer cells." (PMID 38893499, 2024). "Moreover, interferon regulatory factor 1 (IRF1) regulates PANoptosis to prevent CRC 13, and PANoptosis-based molecular clustering and prognostic signature predict patient survival and immune landscape in cancer." (PMID 38169587, 2024). "However, the possibility that targeting ATXN3 in non-cancer cells may alter immune functions as a result of accelerated STAT3, IRF1, and HIF-2α degradation cannot be excluded." (PMID 38038129, 2023). "Interestingly, our study also revealed hub genes (MEG3, MIAT, IRF1, ADAMTS9-AS2, TP63, NOD2, NOD1, NLRP3, MAGI2-AS3, and PVT1, respectively) within the pyroptosis-related ceRNA network, some of which have been well-studied in the field of cancer biology." (PMID 37511974, 2023). "There is also evidence that IRF-1 regulates both second mitochondria-derived activator of caspases (SMAC) and the pro-inflammatory response, suggesting that its up-regulation in human cancers could favor apoptosis." (PMID 29599126, 2018). "Further study indicated the IRF1 seemed to play a key role in the transcriptional activation of interferon-inducible guanylate binding proteins (GBP1 and GBP2), which subsequently induces T-lymphocyte immune response against the cancer cell spreading and proliferation." (PMID 27806724, 2016). "In addition to genetic alterations of IRF-1 genotypes, several additional mechanisms by which IRF-1 may be inactivated in cancer have been reported." (PMID 23420765, 2013). "Importantly, coexpression of IRF1 and STAT3 in ATXN3-KO cancer cells fully rescued IFN-γ–induced PD-L1 expression, but had little effect on hypoxia-induced PD-L1 expression, confirming that ATXN3 promotes IFN-γ–induced PD-L1 expression specifically through stabilizing IRF1 and STAT3." (PMID 38038129, 2023).
bacterial infections (9 papers, 2015 to 2025). "On the one hand, IRF1 can enhance immune responses, inhibit viral replication, and reduce bacterial infections by regulating certain anti-inflammatory factors." (PMID 40420582, 2025). "A large number of studies revealed that PARP-1 interacts with other transcription factors, mainly interferon regulatory factor 1 (IRF1) and participates in cell defense against viral and bacterial infections." (PMID 36289716, 2022). "The function of IRF1 following bacterial infections is incompletely understood, although it appears essential for IFN-related inflammasome activation during Francisella novicida infection indicating a role in IFN and proinflammatory responses following pathogenic bacterial exposure." (PMID 35990635, 2022). "In addition, we found the SGC3 group expressed a cohort of immune-related genes, such as vimentin (Vim) and interferon regulatory factor 1 (Irf1), indicating these cells might participate in defending DRGs against viral or bacterial infections." (PMID 39083491, 2024). "We noted a significant increase in IRF-1 protein level in WT cells following bacterial infection compared to the non-infected cells." (PMID 39850894, 2024). "This set comprises a number of well characterised ISGs including Mx, viperin, IRF1 and CD9 amongst others that are strongly up-regulated by the virus, while fold changes after bacterial infection are much lower and reflect the reduced magnitude of the IFN response triggered in this context." (PMID 26487553, 2015).
infectious disease (8 papers, 2007 to 2023). A disorder directly resulting from the presence and activity of a microbial, viral, or parasitic agent in humans. "Additionally, the disease/function networks that associated with AGE downregulated Casp1, Tlr3, Serp1, Irf1, Irf5, and Irf7 genes were involved in the antimicrobial response, inflammatory response, and infectious diseases." (PMID 27734935, 2016). "Overall, these findings define IRF1 as an upstream regulator of PANoptosis and suggest that modulating the activation of molecules in the IRF1 pathway could be used as a strategy to treat inflammatory and infectious diseases associated with aberrant inflammatory cell death." (PMID 37557956, 2023). "This was the difference with a previous study in Chinook salmon embryo (CHSE-214) cells, which showed that IRF1 was stably expressed in the infected cells from 0–48 hpi after infectious pancreatic necrosis virus (IPNV) infection." (PMID 32290244, 2020). "Of note, although IRF1 signals are essential for infectious diseases and for the inflammatory response of TLR4, IRF1, NF-κB2 and STAT2 were predicted to exhibit higher activation under TLR3 stimulation." (PMID 26159724, 2015).
gastrointestinal tumor (4 papers, 2020 to 2025). "In summary, IRF-1 plays a multifaceted role in the progression of gastrointestinal tumors, primarily through the IFN-γ/STAT1 pathway." (PMID 40909948, 2025). "During liver IR, ROS promote expression of the early response transcription factor IRF-1, enhance activity of histone acetyl transferase, and promotes acetylation of HMGB1." (PMID 33013386, 2020). "In summary, this study provides novel evidence that IRF1 induces autophagy in part by inhibiting the β-catenin pathway during liver IR." (PMID 33137133, 2020). "In addition to regulating the expression of immune escape-related factors, IRF-1 can also act as an oncogenic protein in gastrointestinal tumors." (PMID 40909948, 2025).
adenocarcinoma (3 papers, 2013 to 2020). A common cancer characterized by the presence of malignant glandular cells. "The protein levels of ATF4, eIF2α, and IRF1 were correlated with that of PDL1 in all the tissues except the normal one of adenocarcinoma." (PMID 30305853, 2018). "The level of IRF1 was correlated with that of STAT1 in the normal tissue of adenocarcinoma." (PMID 30305853, 2018).
inflammation (3 papers, 2021 to 2025). Aberrant reaction of the microcirculation characterized by movement of fluid and leukocytes from the blood into extravascular tissues. "In summary, our data demonstrate a novel role for Ataxin-10 in the regulation of TNF-α-induced endothelial inflammation via suppressing IRF-1." (PMID 34858081, 2021). "IRF1 and REL, a member of the NF-κB family, are key mediators of VCAM1 expression during endothelial inflammation." (PMID 35406678, 2022).
neurodegenerative disease (3 papers, 2015 to 2025). A disorder of the central nervous system characterized by gradual and progressive loss of neural tissue and neurologic function. "The role of the IRF family, especially IRF1, 3, and 7, in neuroinflammation has now been widely reported in AD as well as in neurodegenerative diseases." (PMID 40243463, 2025). "Thus, the downregulation of Irf1, Irf7, and Irf9 through JQ1 could inhibit neurodegenerative diseases as well as brain inflammation." (PMID 25890327, 2015).
cardiovascular disease (2 papers, 2019 to 2025). "Regulating IRF1 sulphenylation by supplementation of SO2 donors or AAT1 activators would be a promising approach to the development of new antagonistic therapies against aging and aging-related cardiovascular diseases." (PMID 40223932, 2025).
connective tissue disorder (1 paper, 2015). A disease involving the connective tissue. "We also find evidence for activation of multiple other inflammatory and connective tissue-disorder pathways mediated through pro-inflammatory TF genes such as STAT3, IRF1 and IRF7, CEBPB and SMAD4." (PMID 26202100, 2015).
IRF1 also shares sentences with these, for which no sentence is quoted: bladder cancer (4 papers); immune disorder (3); juvenile idiopathic arthritis (3); liver (3); viral disease (3); acne (2); acute respiratory distress syndrome (2); breast invasive carcinoma (2); central nervous system demyelinating disease (2); epilepsy (2); gastrointestinal disease (2); heart failure (2); Lung Squamous Cell Carcinoma (2); Myelodysplasia (2); oral cancer (2); Parkinson disease (2); renal cell carcinoma (2); Sjögren’s syndrome (2); systemic sclerosis (2); thyroid carcinoma (2); uveal melanoma (2); AIDS (1); allergic rhinitis (1); Allergy (1); alopecia areata (1); amyotrophic lateral sclerosis (1); Azoospermia (1); bacterial Sepsis (1); basal cell carcinoma (1); blood cancers (1).
A further 63 diseases each share a sentence with IRF1 in 1 paper.